STAT3 (signal transducer and activator of transcription 3)
Diseases named in the same sentence as STAT3 in open-access papers (continued):
Sharing a sentence is not in itself a finding about the gene and the disease.
tumor (continued). "Persistent STAT3 activation promotes tumor growth, and elevated STAT3 expression has been documented in iCCA tissues." (PMID 41226789, 2025). "Inhibiting IL-6/JAK/STAT3 signaling has been found to slow tumor development and reinstate chemosensitivity." (PMID 40868199, 2025). "It facilitates tumor cell proliferation, survival, and migration through the activation of signaling pathways such as signal transducer and activator of transcription 3 (STAT3), concurrently impairing the body’s anti-tumor immune responses." (PMID 41394878, 2025). "In gastric cancer, specific microbial configurations correlate with activation of tumor-promoting pathways such as NF-κB and IL-6/STAT3, which enhance tumor growth, angiogenesis, and immune evasion." (PMID 41189901, 2025). "STAT3 is also highly correlated with the tumor‐aggressive phenotype, contributing to a worse prognosis in cancer." (PMID 41090323, 2025). "In an in vivo experiment, garcinol suppressed tumor growth in STAT3-activated xenografts, reducing CSC markers." (PMID 41303402, 2025). "Future research should focus on developing EGFRvIII-targeting approaches, including mRNA vaccines and LCN2/STAT3 inhibitors, while exploring combination therapies that simultaneously address tumor-intrinsic and TME-mediated mechanisms." (PMID 40472740, 2025). "Specifically, ASGR1 interacts with Nemo-like kinase (NLK) to inhibit glycoprotein 130/janus kinase 1 (GP130/JAK1)-mediated STAT3 phosphorylation, thereby blocking the activation of STAT3-related pro-tumor signaling pathways." (PMID 40852369, 2025). "These immunosuppressive cytokines in turn stimulate the oncogenic STAT3 pathway, which hinders the anti-tumor immune response and promotes tumor progression." (PMID 40507329, 2025). "As a central transcriptional regulator, activated STAT3 contributes to chemoresistance and tumor progression through both JAK2-dependent and independent pathways, underscoring its broad relevance as a therapeutic target in gynecologic malignancies." (PMID 41463176, 2025). "STAT3 and STAT5 are the most associated with human cancers and tumor cell lines in response to different oncogenic kinases." (PMID 40003884, 2025). "Interleukin-6 (IL-6) activates the JAK/STAT3 pathway, promoting tumor cell proliferation and immune suppression." (PMID 41311372, 2025). "Phosphorylation of Signal Transducer and Activator of Transcription 3 (STAT3) and activation of Janus kinases (JAKs) are two mechanisms by which interleukin-6 (IL-6) promotes tumour development in cancer." (PMID 41153383, 2025). "Aberrant activation of STAT3 has been widely observed in various cancers, including NSCLC, where it has been implicated in tumor progression, metastasis, and therapeutic resistance." (PMID 40278288, 2025). "Neutralizing IL-17a or blocking JAK2/STAT3 signaling with inhibitor AG490 reduces TAN-mediated tumor migration and invasion." (PMID 40607438, 2025). "OC’s anti-cancer effects arise from its ability to selectively destabilize cancer cell lysosomes, inhibit oncogenic signaling (c-MET/STAT3), and disrupt tumor microenvironment support." (PMID 40564985, 2025). "Inhibition of STAT3 resulted in decreased viability of GBM cells and suppression of tumor growth, consistent with the known role of STAT3 as a critical oncogenic driver in GBM." (PMID 40427146, 2025). "STAT3 promotes several hallmarks of cancer, such as tumour proliferation, metastasis, angiogenesis, immune evasion, inflammation, metabolic reprogramming and cancer growth." (PMID 40507356, 2025). "CD44 cooperates with STAT3 in various tumor types, contributing to cancer invasion, metastasis, disease recurrence, and chemoresistance." (PMID 40438109, 2025). "By reducing STAT3 phosphorylation and nuclear localization, pecan compounds suppress genes controlling survival, angiogenesis, and immune evasion in tumor cells." (PMID 41226270, 2025).
tumor (continued). "Activated STAT3 increases cancer cell proliferation, survival and metastasis, while also inhibiting anti-tumour immunity." (PMID 41298573, 2025). "STAT3 activation is associated with increased interleukin levels, with IL-11 being a crucial cytokine for STAT3 activation and tumor progression." (PMID 40343252, 2025). "Regarding the roles of HRH1 and STAT3 in immune escape, HRH1 was reported to shift macrophages toward an M2-like tumor-associated macrophage (TAM) phenotype, with increased expression of the VISTA immune checkpoint, rendering CD8+ T cells dysfunctional." (PMID 40113769, 2025). "STAT3 promotes cell cycle progression through the G1 and G2/M phases, thereby stimulating tumor cell proliferation and prolonging their survival." (PMID 41007818, 2025). "Persistent activation of STAT3 in response to tumor-derived and host-derived cytokines drives catabolic signaling cascades, disrupts anabolic pathways, and impairs energy homeostasis." (PMID 40704145, 2025). "Leptin also acts as a pro-inflammatory adipokine that induces IL-6 and transforming growth factor β (TGF-β) overexpression and an oncoinflammatory tumor microenvironment development via JAK/STAT3, c-Jun, and Akt pathway activation." (PMID 40227577, 2025). "SNORA28 facilitates radioresistance by recruiting BRD4 to increase H3K9 acetylation at the LIFR promoter, which activates the JAK1/STAT3 pathway and promotes tumor cell proliferation." (PMID 41359051, 2025). "There is also critical functional crosstalk between NF-κB and STAT3, which plays a key role in sustaining inflammation and promoting tumour development." (PMID 41153383, 2025). "STAT3 activity inhibits immunological responses, allowing P. gingivalis and tumor cells to avoid detection and elimination." (PMID 40881676, 2025). "In the nucleus, the STAT3 dimmer binds with the promoter of various oncogenic genes to mediate tumor progression." (PMID 41346572, 2025). "Studies have shown that the activation of the IL‐6/STAT3 signaling pathway in tumor stromal cells, including CAFs, induces the secretion of miRNA‐214 in stromal‐derived EVs, thereby promoting tumor cell extravasation." (PMID 40656546, 2025). "Subsequent research showed that ALYREF binds m5C sites on EGFR mRNA, enhancing transcript stability and activating downstream STAT3 signaling to further drive tumor growth." (PMID 41012587, 2025). "IL-17 signaling triggered activation of STAT3 pathway and NF-κB pathway consequently promotes the release of a variety of proinflammatory factors and chemokines from tumor cells, which can contribute to maintain the proinflammatory reaction locally." (PMID 40055805, 2025). "Mechanistic studies in non-small cell lung cancer revealed that GA suppresses tumor angiogenesis by inhibiting the YAP/STAT3 signaling axis, thereby reducing VEGFR2 expression and effectively cutting off the tumor blood supply." (PMID 41311720, 2025). "Specially, two cytokines, interleukin (IL)-6 and IL-11, which are related to STAT3 signaling, mediate the communication between CAFs and tumor cells along the PAFR/STAT3 axis." (PMID 40033370, 2025). "Further mechanistic exploration revealed that TNF‐α+ Tregs regulate the IL‐13/STAT3 signalling axis, inhibiting tumour stemness and progression." (PMID 40665579, 2025). "A self-assembly nanovaccine, containing the TLR7/8 agonist and STAT3 inhibitor, enhances tumor immunotherapy by augmenting the tumor-specific immune response." (PMID 40573919, 2025). "In OC, the STAT3 pathway is also frequently constitutively active, with its activation level strongly correlating with tumor aggressiveness, chemoresistance, and poor clinical outcomes." (PMID 40799250, 2025). "Research indicates that ASGR1 exerts tumor-suppressive effects by inhibiting phosphorylation of the STAT3 signaling pathway." (PMID 40852369, 2025).
tumor (continued). "This lactate-activated epigenetic reprogramming subsequently leads to CD47 upregulation, which in turn inhibits microglia/macrophage phagocytosis and supports tumor cell immune escape via pathways such as STAT3." (PMID 41463052, 2025). "Both STAT3 and NF-κB play a key role in tumor cell proliferation, migration, increased survival, and resistance to apoptosis in malignant T-cells." (PMID 40733655, 2025). "Other investigations, as well as studies conducted by other groups, have demonstrated that both antibody targeting of STAT3 and stable lentiviral knockdown lead to significant anti-tumor effects in vitro and promote tumor growth in vivo." (PMID 40427146, 2025). "Released quercetin from the quercetin‐Ferrum ion (QFN) suppresses the phosphorylation of JAK2/STAT3 and reduces PD‐L1 expression in tumor cells." (PMID 41195524, 2025). "In colorectal cancer, phosphorylated ATF6 induces gut microbiota dysbiosis and activates the TRIF/STAT3 signaling pathway, accelerating tumor progression." (PMID 41209558, 2025). "TAM‐secreted IFN‐γ stimulates the PI3K/AKT and JAK/STAT3 signaling pathways in A549 cells, increasing PD‐L1 expression and migration in tumor cells." (PMID 39927632, 2025). "Activated EGFR initiates several signaling pathways, including the ERK and STAT3 pathways, which promote cell proliferation, tumor progression, and survival." (PMID 40881676, 2025). "(2024) developed a tumor-targeted delivery platform utilizing tumor-derived extracellular vesicles (TEVs) to co-deliver small interfering RNA against STAT3 (siSTAT3) and the chemotherapeutic agent doxorubicin (DOX), termed siSTAT3-DOX@TEV." (PMID 40936705, 2025). "Tumor‐bearing model mice are often used to examine the ability of silibinin to inhibit STAT3 phosphorylation." (PMID 39907159, 2025). "Tissue inhibitor of metalloproteinases-1 (TIMP1) is a multifunctional matrix metalloproteinase inhibitor that promotes tumor cell survival and angiogenesis by binding to the STAT3 pathway." (PMID 41189944, 2025). "RNLS knockdown suppressed STAT3 expression, cell proliferation, migration, invasion, and tumor growth, while promoting apoptosis, ROS accumulation, and mitochondrial damage." (PMID 40799250, 2025). "In breast cancer, IL-17 signaling through STAT3 contributes to tumor progression and metastasis by increasing neutrophil infiltration and supporting an inflammatory microenvironment that fosters tumor growth." (PMID 40486614, 2025). "We noted that TUBA1B overexpression is linked to key immune-related pathways in the tumor immune microenvironment (TIME), such as IL-6/JAK/STAT3 signaling, IL-2/STAT5 signaling, TGF-Beta signaling, and interferon responses." (PMID 39968182, 2025). "These cytokines act on tumor cells, activating NF-κB and STAT3 pathways, which can then engage in crosstalk with the PI3K/Akt pathway to synergistically enhance cell survival and proliferation 76,77." (PMID 41208895, 2025). "STAT3 plays a critical role in cancer by promoting tumor growth and immune evasion within the tumor microenvironment (TME), particularly through its regulation of cancer-associated fibroblasts." (PMID 39862296, 2025). "Recent studies have also demonstrated that STAT3 activation is involved in shaping the tumor immune microenvironment, particularly by promoting the expression of PD-L1, reducing NK cell infiltration, and polarizing macrophages toward the M2 phenotype." (PMID 41296440, 2025). "By “long-term efficacy”, we refer to the ability of the NLP-EXOSOME COMPLEX to sustain STAT3 inhibition over an extended period and potentially prevent tumor recurrence." (PMID 40427146, 2025).
tumor (continued). "GBM tumor development and growth reduction was suggested due to garcinol abrogating STAT3/5A signaling and upregulating hsa-miR-181d, with concomitant suppression of the Ki-67 proliferation index and enhancement of Bax/Bcl-xL apoptotic ratio." (PMID 41303402, 2025). "Constitutively activated STAT3 promotes immunosuppression through direct regulation of PD-L1 expression and recruitment of immunosuppressive cells to the tumor microenvironment (TME)." (PMID 40347254, 2025). "B7-H3 also activates pro-proliferative signaling through ERK and STAT3 and facilitates cell cycle progression by enabling tumor cells to bypass the G1/S checkpoint." (PMID 41463642, 2025). "By controlling gene expression-related apoptosis, EMT, cell migration, aggregation, and invasion, STAT3 facilitates tumor growth and metastasis in TNBC." (PMID 40943427, 2025). "Upon activation of the IL-6/JAK/STAT3 signaling pathway, the expression of genes such as Cyclin D1 and Bcl-2 is upregulated, promoting tumor cell cycle progression and inhibiting apoptosis, thereby enhancing tumor cell proliferation and survival." (PMID 40909292, 2025). "Many benign and malignant tumours in humans have constitutive STAT3 activation due to aberrant growth factor, cytokine receptor, and Janus kinases (JAK) regulation." (PMID 40061959, 2025). "In GBM, the tumor cells and their secreted factors upregulate STAT3 activity in macrophages, thereby suppressing proinflammatory gene transcription and bolstering immune evasion." (PMID 41002423, 2025). "To understand the involvement of STAT3 signaling in tumor-related neutrophil functions in vivo, we generated a neutrophil-specific STAT3 knockout mouse strain (Ly6GcreSTAT3fl/fl, referred to as NStat3−/−)." (PMID 40885734, 2025). "NF-κB pathway can also interact with JAK/STAT3 to further enhance proliferation and anti-apoptotic capabilities of tumor." (PMID 40535567, 2025). "Collectively, these findings underscore the potential of targeting the STAT3/UBE2S/NKp30 axis as a viable approach to impede NSCLC tumor growth and improve clinical outcomes." (PMID 41254082, 2025). "As STAT3 is a critical transcription factor involved in tumor development and progression, it has emerged as a promising therapeutic target in cancer treatment." (PMID 40227962, 2025). "Growing evidence suggests that STAT1 and STAT3 are indeed playing opposing roles in tumor development, cell proliferation, and cell survival." (PMID 40287766, 2025). "Consistent with the RNA-seq results, western blot analysis showed that the levels of phosphorylated STAT3 (p-STAT3) and total STAT3 protein were significantly increased in GA muscle of KPC tumor-bearing Xbp1fl/fl mice." (PMID 40655023, 2025). "These life-threatening events seem to be triggered by mediators of cellular communication within the tumour system, particularly a high level of IL-6, which activates STAT3 even in normal cells." (PMID 41009413, 2025). "Given the role of STAT3 in promoting tumor growth and survival, its inhibition by CSE highlights a potential mechanism through which CSE exerts its antitumor effects." (PMID 39861616, 2025). "STAT3 follows a similar trend, with enriched expression throughout the tumor regions and strongest levels observed at the core and border." (PMID 41373817, 2025). "In GBM, OSMR cooperates with its ligand OSM to activate STAT3 signaling, inducing a mesenchymal‐like phenotype that enhances tumor invasiveness and treatment resistance." (PMID 41498024, 2025). "Mechanistically, the inhibition of STAT3 phosphorylation is pivotal in mediating the synergistic anti‐tumor effects observed with the combination of IDET and paclitaxel." (PMID 40918170, 2025). "Combining inhibition of HRH1 and STAT3 using their respective inhibitors or short hairpin (sh)RNAs enhanced the tumor-suppressive effects compared to HRH1 inhibition/depletion alone in OSCC cells and a xenograft model." (PMID 40113769, 2025).
tumor (continued). "The TME, particularly CAFs, contributes to gemcitabine resistance via the secretion of cytokines such as IL-6, which activate the STAT3 signaling pathway in tumor cells." (PMID 41425711, 2025). "In summary, these in vivo results demonstrate that CDN effectively inhibits tumor growth by targeting the JAK/STAT3 pathway to promote apoptosis and suppress EMT, while maintaining a favorable biosafety profile." (PMID 41585878, 2025). "Its aberrant activation triggers tumor progression by promoting the expression of oncogenic genes; thus, STAT3 is classified as an oncoprotein." (PMID 40141386, 2025). "Studies have shown that CXCL12/CXCR4 activation leads to downstream STAT3 phosphorylation, promoting transcription of genes related to tumor growth and angiogenesis, such as VEGF, MCL-1, and BCL-XL." (PMID 40607416, 2025). "Together, these data suggest that tumor-induced cytokines promote JAK/STAT3 activity in the liver, which facilitates a metabolic rewiring characterized by an increase in the APR and suppression of PPAR-α activity." (PMID 41278737, 2025). "Sustained IFN-γ signaling, for instance, drives tumor cell adaptation by promoting STAT3-c-Myc-mediated metabolic reprogramming, shifting cellular energy metabolism from oxidative phosphorylation (OXPHOS) toward aerobic glycolysis." (PMID 41359111, 2025). "The IL-6/JAK/STAT3 signaling pathway plays a critical role in regulating the tumor microenvironment, thereby promoting tumor growth, invasion, and metastasis." (PMID 40332515, 2025). "In a murine melanoma model, ST targeting the immune-suppressive factor STAT3 enhanced the immune response, reduced tumor growth, and improved survival when combined with tumor antigen vaccination." (PMID 39859231, 2025). "Our data further demonstrate that tumor-derived LCN2 plays a critical role in mediating EGFRvIII-induced fibroblast activation via the STAT3 signaling pathway." (PMID 40472740, 2025). "BP1003 reduces STAT3 expression, enhances sensitivity to paclitaxel and 5-FU, reduces tumor growth, and blocks pro-tumorigenic M2 macrophage polarization, with potential in immunotherapy." (PMID 40330466, 2025). "In general, the expression level of STAT3 is higher in tumor cells as compared to the normal cells and is beneficial for the proliferation of tumor cells and anti-apoptosis." (PMID 40302804, 2025). "IL-6, together with its soluble receptor, activates GP130 and the JAK/STAT3 cascade, leading to inflammatory cytokine expression, apoptosis resistance, and tumor growth." (PMID 41155242, 2025). "The inhibition of the STAT3 signaling pathway by these NPs also contributed to a reduction in tumor spheroid formation in a three‐dimensional model." (PMID 40166646, 2025). "As expected, western blot analysis of tumor tissues confirmed that phosphorylated STAT3 levels were reduced in the bazedoxifene group compared to vehicle control." (PMID 41148817, 2025). "Tryptophan metabolite Indole‐3‐aldehyde (I3A) downregulates cytosolic AhR and p‐ERK/c‐MYC proteins, together enhancing STAT3 phosphorylation and tumor immunogenicity." (PMID 40583248, 2025). "In CAC mice, miR-21 removal boosted tumor cell mortality, which was followed by a decline in STAT3 and Bcl-2 activation." (PMID 41476448, 2025). "Both STAT3 and NF-κB are canonical mediators of tumor-promoting inflammation, and their elevated activity in proximal tumors supports the presence of a cytokine-rich, immune-active milieu." (PMID 40862793, 2025). "It has been demonstrated that the STAT3 signaling pathway significantly influences tumor cell growth, reproduction, metastasis, and apoptosis." (PMID 40487290, 2025). "Given the critical role of STAT3 in tumor growth and progression, targeting the STAT3 signaling pathway represents a promising therapeutic strategy." (PMID 40278288, 2025). "Activated STAT3 drives tumor progression by regulating the expression of genes involved in survival, proliferation, angiogenesis, and immune escape." (PMID 41041638, 2025).